IL11 (interleukin 11)
Diseases named in the same sentence as IL11 in open-access papers (continued):
Sharing a sentence is not in itself a finding about the gene and the disease.
inflammatory bowel disease (9 papers, 2010 to 2024). A spectrum of small and large bowel inflammatory diseases of unknown etiology. "In models of inflammatory bowel disease, the up-regulation of gp130 signalling mediated by elevated levels of tumor IL-6 and IL-11 leads to Yap1 activation as a mechanism of wound healing." (PMID 37957015, 2024). "IL11 mRNA levels are also increased in the affected tissue of patients with inflammatory bowel disease (IBD) and upregulation of this cytokine is found most pronounced in patients with intestinal fibrosis." (PMID 38455057, 2024). "Given that IL11 expression in colonic stromal cells predicts anti-TNF therapy failure in patients with ulcerative colitis or Crohn’s disease, we suggest IL11 as a therapeutic target for inflammatory bowel disease." (PMID 31917819, 2020). "IL-11 has also been shown to play a role in decreasing mucosal damage in inflammatory bowel disease and decreasing the severity of acute necrotizing pancreatitis." (PMID 22715999, 2012). "Interestingly, IL11 expression in smooth muscle cells demonstrated signs of neuroinflammation in the myenteric plexus, which has been observed in inflammatory bowel disease." (PMID 31917819, 2020). "We also confirmed published reports of elevated IL11 expression in inflammatory bowel disease (IBD)." (PMID 38455057, 2024). "Similarly, in inflammatory bowel disease (IBD), fibroblasts contribute to inflammation through the secretion of factors like IL-11, IL-24, and IL-13RA2." (PMID 39290699, 2024). "In humans STAT3 represents one of the disease loci for Crohn's and inflammatory bowel disease (IBD), and most likely relates to the capacity of Stat3 to promote intestinal barrier function and integrity in response to IL6, IL11 and IL22 exposure." (PMID 20478049, 2010). "Previous research on patients with inflammatory bowel disease (IBD) has identified several genes (IL13RA2, TNFRSF11B, STC1, IL-6, and IL-11) that constitute potential biomarkers that can identify patients with limited response to IFX, which is consistent with our study." (PMID 34650991, 2021).
myocardial infarction (9 papers, 2015 to 2024). Gross necrosis of the myocardium, as a result of interruption of the blood supply to the area, as in coronary thrombosis. "The treatment with IL-11 recombinant specie-specific, rmIL-11, in the model of myocardial infarction, induced an increase in cardiac fibrosis associated with left ventricular impairment." (PMID 38392279, 2024). "Additionally, elevated serum concentration of IL-11 is associated with cardiovascular events in patients with heart failure such as sudden cardiac death, myocardial infarction, and stroke." (PMID 38093747, 2023). "Studies in knockout mice for the IL-11Rα receptor demonstrated protection against fibrosis while IL-11 treatment in the myocardial infarction model induced decreased cardiac fibrosis." (PMID 38392279, 2024). "Cardiac IL-11 expression in a murine model is elevated in ischemia/reperfusion-induced myocardial infarction, cardiac fibrosis induced by angiotensin II (Ang II), transverse aortic constriction (TAC), and ascending aortic constriction (AAC)." (PMID 38392279, 2024). "For rhIL-11 treatment in ischemia/reperfusion-induced myocardial infarction models, the effects of IL-11 improved cardiac function, with increased LVDP, ±dP/, and reduction in the size of the infarct area." (PMID 38392279, 2024). "Further studies have revealed antifibrotic and cardioprotective effects of IL-11 using recombinant human IL-11 instead of recombinant mouse IL-11 in mouse models of myocardial infarction, ischemia-reperfusion injury, and cold-ischemia." (PMID 38093747, 2023). "Therefore, Inhibition of IL-11 positively affected the rehabilitation of myocardial infarction and postoperative complications." (PMID 37304948, 2023). "Although most studies have reported a protective role for IL-11 after acute myocardial infarction (AMI), it is not known whether IL-11 is involved in plaque formation, development, and rupture in CHD." (PMID 26098632, 2015).
Stroke (9 papers, 2017 to 2025). Sudden impairment of blood flow to a part of the brain due to occlusion or rupture of an artery to the brain. "In the pathological process of stroke, IL-11 can upregulate the expression of vascular cell adhesion molecule-1 (VCAM-1) through its proinflammatory effects, leading to vascular inflammation and injury." (PMID 39787159, 2025). "Specifically, PPARα KO led to increased expression levels of Gadd45b, Nppa, Hdc, Lcn2, Il6, Sox4, Marcksl1, Saa3, Ucn2, Met, Dusp10, Elovl7, Ngf, C3, Il11, Hmox1, Alox5, Tnfsf9, Angptl4, Plin2, H19, Csf2rb, Atf3, and Col7a1 following stroke." (PMID 40362325, 2025). "Previous studies in animal models and in stroke patients have shown that continued production of cytokines such as IFNγ, TNFα, IL11, IL-1β, IL-1ra and IL-6 induces and maintains the M1 polarization state." (PMID 30584250, 2018). "A large fraction of these genes such as Hmgb2, TNF and IL-11 were pro-inflammatory factors Cluster two genes such as Ctss and PTPN18are either peptidases or proteases that were expressed at 3 days and peaked 7 days after stroke onset." (PMID 34094642, 2021). "Some circulating cytokines and reactive molecules, such as interleukin 11 (IL-11), are considered important markers of ischemic stroke, though some consideration should be taken into account about the role of the different subtypes of stroke." (PMID 28373915, 2017). "Comparative studies across experimental stroke models could also help delineate whether the neuroprotective, inflammatory, and fibrotic roles of IL-11 are universally conserved or uniquely adapted to the specific pathophysiology of ICH, thereby refining potential therapeutic strategies." (PMID 41487426, 2025). "Thus, MLC601 and MLC901 reduce infarct size and ischemia-induced neurological deficits, attenuate cerebral ischemia-induced pro-inflammatory cellular infiltration, and attenuate stroke-induced increased expression of pro -inflammatory mediators (IL11, IL1β, IL6 and TNFα) in the brain." (PMID 36975881, 2023). "We validated the selective expression of IL11 protein in pericytes after stroke using immunohistochemistry, showing IL11 exclusively colocalizing with pericytes, and not with neurons or other cell types." (PMID 37378751, 2024). "In addition, our data also revealed that Il11 expression is only upregulated in pericytes in the stroke-specific subcluster 5 but absent in the contralateral pericytes or in other cell types." (PMID 37378751, 2024).
COVID-19 (8 papers, 2021 to 2024). A disease caused by infection with severe acute respiratory syndrome coronavirus 2. "Although many of the cytokines detected in the study have already been reported as possible diagnostic marker candidates, IL-11 might also be a novel diagnostic marker candidate in COVID-19." (PMID 38476443, 2024). "In the present study, we analyzed IL-6, IL-11, sIL-6R, sgp130 and sCD25 in the serum of healthy, uninfected subjects, in COVID-19 convalescent individuals with a history of mild COVID-19 disease and in acute severely ill COVID-19 patients." (PMID 39835136, 2024). "Although few studies have reported IL-11 in COVID-19, IL-11 might be a novel cytokine marker candidate in COVID-19." (PMID 38476443, 2024). "Further studies using e.g. bronchoalveolar lavage or even tissue biopsies from patients would be able to determine whether IL-11 might be present in higher amounts locally in the lung tissue of COVID-19 patients and thereby contribute to inflammatory or pro-fibrotic processes." (PMID 39835136, 2024). "Thus, we hypothesize that IL-6 upregulation in COVID-19, as well as IL-3 and IL-11 upregulation, is likely involved in the stimulation of megakaryocytes and possibly also resident megakaryocytes in the lung." (PMID 38786077, 2024). "In addition, we proposed a hypothetical model that SDF-1, SCYB16, IL-11, sCD30, and I-309 might all play a pivotal role in helper T-cell differentiation and excessive cytokine release with immune response and inflammation in COVID-19." (PMID 38476443, 2024). "A previous set of cytokine quantification assays performed in a pilot screening of plasma soluble proteins with COVID-19 and CAP patients revealed differences in the plasma levels of IL-11, IL-17 and the tissue inhibitor of metalloproteinases 2 (TIMP-2)." (PMID 35087533, 2021). "We also show that IL-11 has no major systemic role in COVID-19 patients and that sCD25 is only increased in acute severely ill COVID-19 patients, but not in mild convalescent individuals." (PMID 39835136, 2024). "In contrast to IL-6, we observed no increase in serum levels of IL-11 in COVID-19 patients." (PMID 39835136, 2024).
systemic sclerosis (8 papers, 2020 to 2024). A chronic disorder, possibly autoimmune, marked by excessive production of collagen which results in hardening and thickening of body tissues. "Of note, CCL2 levels were correlated with the extent of skin fibrosis in systemic sclerosis, a pathogenic feature also triggered by IL11 expression in SMCs." (PMID 31917819, 2020). "There is growing evidence for a pathogenic role for IL11 in skin and lung fibro-inflammation in systemic sclerosis (SSc)." (PMID 38054591, 2023). "Using the same approach, we observed a trend that IL11 and its receptor transcripts were expressed in systemic sclerosis (SSc) patient skin keratinocytes with sporadic signals detected in infiltrated immune cells in SSc patient skin samples." (PMID 38455057, 2024). "This is exemplified by systemic sclerosis, which presents with global organ fibrosis and specific vascular abnormalities and is characterized by elevated transforming growth factor beta (TGFB) 2 and interleukin 11 (IL11) expression in dermal stromal cells." (PMID 31917819, 2020).
ulcerative colitis (8 papers, 2015 to 2024). An inflammatory bowel disease involving the mucosal surface of the large intestine and rectum. "In humans, expansion of IL-11+ IAFs was recently described in ulcerative colitis and Crohn’s disease patients." (PMID 35085231, 2022). "Recent single-cell RNA-Seq data have shown an association between inflammatory-type fibroblasts (IL13RA2+-IL11+), IL-11, and Crohn’s disease and ulcerative colitis." (PMID 32897876, 2020). "In this study, we investigated the Fra-1 gene expression in the inflamed mucosa of patients with ulcerative colitis (UC) as well as its relation to IL-11 expression." (PMID 29914371, 2018). "In this study, we will examine the IL-11 protein amount in the inflamed colonic tissue of the patients affected by ulcerative colitis." (PMID 29914371, 2018). "Several reports show that IL-11 stimulate and accelerate the development of ulcerative colitis, promote the tumor progression by activating the STAT3 and suppress the antitumor immune response." (PMID 26528857, 2015). "In addition, oxidative stress in inflamed intestinal biopsies induced FOSL1 gene expression, thereby promoting the expression of IL11 in ulcerative colitis patients." (PMID 37153732, 2023). "IL11 ISH studies in Crohn’s disease (CD) and Ulcerative Colitis (UC) patient colon resection samples showed significantly higher transcript levels compared to control colon tissue." (PMID 38455057, 2024). "In humans, IL11 is highly upregulated in the colonic mucosa of patients with either ulcerative colitis or Crohn’s disease who do not respond to anti-TNF therapy, with recent single cell RNA-seq studies localizing IL11 to inflammatory mucosal stromal cells." (PMID 31917819, 2020).
acute kidney injury (7 papers, 2020 to 2024). Sudden and sustained deterioration of the kidney function characterized by decreased glomerular filtration rate, increased serum creatinine or oliguria. "And, that IL11 up-regulation in a mouse model of CKD causes renal failure and that anti-IL11 therapy can reactivate endogenous renal repair mechanisms by reversing SNAI1-driven pEMTof TECs to promote kidney regeneration and recovery of function." (PMID 38054591, 2023). "IL11 secretion from damaged podocytes, and stressed TECs in particular, causes TEC pEMT and dysfunction, fibro-inflammation, and renal failure." (PMID 38054591, 2023). "Mice with acute kidney injury upregulate IL11 in TECs leading to SNAI1 expression and kidney dysfunction, which is not seen in Il11 deleted mice or in mice administered a neutralizing IL11 antibody in either preemptive or treatment modes." (PMID 36470928, 2022). "In CKD, anti-IL11 was associated with TEC proliferation, restoration of kidney parenchymal mass and reversal of renal failure." (PMID 36470928, 2022). "IL11 is an important downstream regulator of TGF-β and has been recently described as a pro-fibrotic factor in fibroblasts as well as in a mouse model of acute kidney injury." (PMID 37571269, 2023).
Crohn disease (7 papers, 2017 to 2024). A gastrointestinal disorder characterized by chronic inflammation involving all layers of the intestinal wall, noncaseating granulomas affecting the intestinal wall and regional lymph nodes, and transmural fibrosis. "Making use of recombinant human IL-11 able to maintain remission phase in Crohn’s disease." (PMID 29914371, 2018).
heart failure (7 papers, 2019 to 2025). Inability of the heart to pump blood at an adequate rate to meet tissue metabolic requirements. "Recent studies have revealed IL-11’s complexity in cardiovascular diseases, particularly in developing CF and the chronic activation of the IL-11 signaling pathway associated with heart failure." (PMID 39877631, 2025). "This study clarified the relationship among miR‐30c, lncRNA‐CASC7 and IL‐11 expression and the risk of heart failure and showed that lncRNA‐CASC7 is potentially involved in the pathogenesis of HF via modulating the expression of miR‐30c." (PMID 32860492, 2020). "Recent research on IL-11 further highlights its role in inducing heart failure, hypertrophy, and fibrosis." (PMID 39678250, 2024). "In human and non-human primate studies, exogenous IL11 causes heart failure symptoms, myocardial hypertrophy, and elevation of serum B-natriuretic peptide levels." (PMID 37629170, 2023). "However, there have been no studies about the role of IL-11 in heart failure (HF)." (PMID 30728748, 2019).
Hypertension (7 papers, 2020 to 2024). The presence of chronic increased pressure in the systemic arterial system. "In preeclampsia, IL11 levels are elevated and cause hypertension and spiral artery remodelling." (PMID 38054591, 2023). "IL11 levels are elevated in the kidney in a number of species in response to varied injuries that include diabetes, hypertension, ischaemia, toxins, infective agents (bacterial and viral), preeclampsia and obstructive nephropathy." (PMID 38054591, 2023). "Restricting Asc loss to the placenta and fetus was sufficient to protect against IL11-induced hypertension during pregnancy and at 50 days post-natal, indicating IL11 drives hypertension via placental-inflammasome activation in this mouse model." (PMID 37292200, 2023). "This study also focuses on the role of IL-11 in coronary artery disease, hypertension, pulmonary hypertension, cerebrovascular disease, aortic disease, and other vascular diseases and its potential as a therapeutic target." (PMID 37304948, 2023). "Evidence has shown that IL-11 promotes pregnancy-induced hypertension in preeclampsia (PE)." (PMID 37304948, 2023). "This evidence suggests that IL-11 promotes the occurrence of hypertension." (PMID 37304948, 2023). "Moreover, exogenous IL11 administration to pregnant mice during mid-gestation recapitulates preeclampsia-like features: hypertension, proteinuria, fetal growth restriction, and pre-term birth." (PMID 37292200, 2023). "In this work we assumed the hypothesis that IL-11 mediates pulmonary artery remodeling and hypertension promoting EnMT and HPASMC-myofibroblast-like transition that resembles to previously observed in lung fibroblasts." (PMID 36376885, 2022). "However, this study also indicates that simply inhibiting placental inflammasome activity to prevent preeclampsia-associated hypertension does not protect against placental insufficiency and inhibiting IL11 action is also required to improve fetal outcomes." (PMID 37292200, 2023). "As our in vivo data demonstrated that activation of the placental inflammasome is required to induce hypertension in our mouse model of preeclampsia, we investigated whether IL11 regulated expression of genes likely to drive hypertension via inflammasome activation." (PMID 37292200, 2023). "Under AngII-induced hypertension, ALKBH5 mediated m6A demethylation of IL-11 mRNA to increase the stability IL-11, promoting AngII-induced MMT, and resulted in cardiac fibrosis." (PMID 39220683, 2024). "Under AngII-induced hypertension, ALKBH5 mediated the m6A demethylation of IL-11 mRNA, leading to increased stability and protein level of IL-11, promoting AngII-induced MMT, resulting in cardiac fibrosis and functional impairment." (PMID 39220683, 2024). "Taken together, the present study provides direct evidence that transition of macrophages to myofibroblasts is involved in the process of hypertension-induced cardiac fibrosis, which is largely dependent on the ALKBH5-decreased m6A-demethylation on IL-11 in cardiac macrophages." (PMID 38443404, 2024). "Specific deletion of ALKBH5 in macrophage inhibits hypertension or pressure overload induced MMT, and subsequently attenuates pathological cardiac fibrosis and diastolic dysfunction, via regulating m6A modification on IL-11 mRNA." (PMID 38443404, 2024).
Lipedema (7 papers, 2021 to 2025). Disorder of adipose tissue characterized by symmetric and bilateral enlargement of the lower extremities due to abnormal deposition of subcutaneous fat often in obese women. "A multiplex immunoassay analyzing 37 cytokines in lipedema serum samples identified 22 cytokines present in the condition, with significantly elevated levels of IL-11, IL-28A, and IL-29." (PMID 41303617, 2025). "Both IL-28A and IL-29 are secreted by macrophages, and IL-11 promotes the proliferation of adipose-derived stem cells while inhibiting adipogenesis, contributing to the hyperplasia seen in lipedema." (PMID 41303617, 2025). "Of these cytokines, IL-11 is known to regulate adipogenesis and is mostly secreted by stromal vascular cells, which are present in increased numbers in the adipose tissue of lipedema patients." (PMID 37887430, 2023). "Slightly elevated concentrations of three (IL-11, IL-28A and IL-29) out of 39 evaluated inflammatory proteins were recently shown in the serum of lipedema patients." (PMID 36387874, 2022). "The comparison between lipedema and control patients (pre-operatively) revealed significantly increased IL-11, interferon type III family IL 29 (interferon lambda 1) and IL28A (interferon lambda 2) levels." (PMID 33805070, 2021). "The alterations in circulating IL11, IL28A and IL29 levels are possibly linked to the specific immunological niche present in lipedema." (PMID 33805070, 2021). "The primary source for IL-11 is the stromal vascular fraction which is increased in adipose tissue of lipedema patients." (PMID 33805070, 2021). "Several of the cytokines found to be elevated in females with lipedema, for example, VEGF-A, VEGF-C, IL-11, IL-28A, and IL-29, were below the detection limit or not included in the analysis kit in this study." (PMID 40125475, 2025).